ENSG00000196826 (novel zinc finger protein)
Gene: Protein-coding gene on chromosome 19 (12,461,559 to 12,551,474, reverse strand). Ensembl gene ENSG00000196826.
Genetic constraint (gnomAD): Loss-of-function variants: 13 observed, 11.03 expected, observed/expected ratio (o/e) 1.18, 90% interval 0.76 to 1.78. Missense variants: 589 observed, 781.71 expected, observed/expected ratio (o/e) 0.75, 90% interval 0.7 to 0.81. Synonymous variants: 194 observed, 233.64 expected, observed/expected ratio (o/e) 0.83, 90% interval 0.74 to 0.94.